IL17A (interleukin 17A)
Diseases named in the same sentence as IL17A in open-access papers (continued):
Sharing a sentence is not in itself a finding about the gene and the disease.
tumor (continued). "Our results suggested that Th17 cells percentage was lower in DLBCL tumor tissues than in PBMCs or corresponding adjacent benign tissues; accordingly, the level of IL-17A was also lower in tumor tissues than in benign tissues, and the expression of IFN-γ was the opposite." (PMID 28537908, 2017). "At the same time, the Ma S group found that the CXCL5 production of tumor cells could be induced by IL-17A, and the infiltration of MDSCs in tumor sites was mediated by CXCL5/CXCR2." (PMID 28002798, 2017). "Meanwhile, IL-17A mRNA levels were significantly increased in PDL1high tumor tissues (p < 0.05)." (PMID 27935862, 2017). "Absence of MDA-9/Syntenin in the lung microenvironment suppressed tumor growth by modulating in situ Interleukin 17A (IL17A) expression and impaired the recruitment of myeloid derived suppressor cells (MDSCs) and Th17 cells as compared to genetically wild type animals." (PMID 27341128, 2016). "Furthermore, LDH assay showed that IL-17A enhanced the direct cytolytic effect of B cells against ESCC tumor cells." (PMID 26942702, 2016). "Furthermore, TNF-α and IL-17A are thought to have synergistic tumor promoting properties when expressed together in CRC cells, whereby these cytokines stimulate glucose metabolism and growth factor production." (PMID 27014625, 2016). "On the other way, IL-17A could enhance the tumor killing capabilities of B cells by producing more immunogenic antibody and cytolytic molecules." (PMID 26942702, 2016). "IL-17A could stimulate ESCC tumor cells to produce much more chemokines to recruit more immune cells to the tumor microenvironment and enhances their antitumor functions." (PMID 26942702, 2016). "On one way, IL-17A could promote the migration of B cells by stimulating tumor cells to produce much more chemokines." (PMID 26942702, 2016). "IL-17A could stimulate ESCC tumor cells to produce much more chemokines, such as CCL2, CCL20 and CXCL13." (PMID 26942702, 2016). "In addition, IL-17A enhanced the IgG-mediated antibody and complement mediated cytotoxicity of B cells against tumor cells." (PMID 26942702, 2016). "Furthermore, blockade of Nrp-1 resulted in significantly augmented tumor-derived CD4+IL-17A+ (Th17) cells." (PMID 27075020, 2016). "This study provides further understanding of the roles of IL-17A in humoral response, which may contribute to the development of novel tumor immunotherapy strategy." (PMID 26942702, 2016). "IL-17A could promote the ESCC tumor cells to produce more chemokines CCL2, CCL20 and CXCL13, which were associated with the migration of B cells." (PMID 26942702, 2016). "We subsequently tested whether digoxin (shown to inhibit IL-17A production and possibly tumour metastasis) and SR1001 (described to impede the differentiation and function of TH17 cells) could reduce LRV1 mediated disease severity in our murine model." (PMID 27658195, 2016). "We did not explore the molecular mechanism in detail, but it is possible that other resident cells of the tumor microenvironment such as macrophages or T cells might produce IL-17A as a consequence of the presence of localized tumor cells." (PMID 27341128, 2016). "The studies concerning the roles of IL-17A in tumor development are still controversial." (PMID 26942702, 2016). "Overexpression of IL-17A might then facilitate the suppression of the host-mediated immune surveillance and allow the tumor cells to grow in mda-9−/− mice, as evident in day 15 or later time points." (PMID 27341128, 2016). "In our previous studies, we found that IL-17A could mediate anti-tumor immunity by recruiting immune cells to the tumor microenvironment, such as NK cells, CD8+ T cells and CD1a+ DCs." (PMID 26942702, 2016). "Interestingly, only a fraction of human T cells from either tumor or tonsil co-expresses both RORγt and IL-17A, while a significant fraction expresses either IL-17A or RORγ alone." (PMID 28123897, 2016).
tumor (continued). "IL-17A deficient-Apc/Min+ mice have very few tumors by 6-7 weeks, and thus Treg from this strain have not yet encountered a mature tumor microenvironment." (PMID 26146642, 2015). "Taken together, these results suggest that elevated levels of IL-21 in the tumors of Apcmin/+ mice support a tumor-promoting inflammatory microenvironment characterized by enhanced production of IL-17A, IL-22, TNF-α and IL-6 and hyper-activation of STAT3/NF-kB." (PMID 25839161, 2015). "It would be interesting to test whether anti-IL-17A, IL-17B and/or IL-17E based therapies could affect tumor growth and sensitivity to chemotherapy and immunotherapy (anti-HER2) in animal models of cancer." (PMID 26154409, 2015). "It is well-known that a controversy has been existed for a long time around the question of whether IL-6 and IL-17A are anti-tumor or tumor promoting factors." (PMID 25826372, 2015). "Thus, the tumor microenvironment in Apc/Min+ mice have markedly increased numbers of Foxp3+ Tregs but only moderately increased IL-17A+ CD4 T cells in the LP, suggesting that Apc/Min+ Foxp3+ Tregs are altered in the LP." (PMID 26146642, 2015). "Inaddition, λ-carrageenan could enhance the secretion of IL17A in spleen andsignificantly increase the level of TNF-α in tumor, most of which wassecreted by infiltrating macrophages." (PMID 26098663, 2015). "Interleukins are known to promote tumor growth and metastasis, and IL-17A could be a typical example." (PMID 26154409, 2015). "Furthermore, the cytotoxic activity of tumor infiltrating CD8+ lymphocytes in mice treated with Ad-si-IL17A was significantly higher than in control mice." (PMID 25590298, 2015). "Finally, serum IL-17a and tumor MC IL-17a mRNA levels were significantly increased after OVA plus AOM/DSS versus AOM/DSS alone." (PMID 26429861, 2015). "Foxp3+RORγt+ T regulatory cells (Tregs) expand in CRC patients and may contribute to tumor development in part through the synthesis of IL-17A." (PMID 25839161, 2015). "IL-23A may induce the secretion of IL-17A activate IL-17A/IL-17RA/NF-κB signaling in tumor microenvironment." (PMID 25349535, 2014). "This suggests that other factors in addition to IL-17A might promote tumor growth in pre-irradiated beds." (PMID 25181290, 2014). "IL-23A can promoted GC cells growth by inducing the secretion of IL-17A in tumor microenvironment." (PMID 25349535, 2014). "Furthermore, IL-17A enhanced the cytotoxic effects of NK cells against tumor cells by augmenting the expression of cytotoxic molecules." (PMID 24905806, 2014). "IL-17A seems to be a key factor for enhancing tumor growth in pre-irradiated tumor beds." (PMID 25181290, 2014). "Accordingly, irradiation-induced IL-6 and TGF-β could act separately as a pro-tumor factor as well as accelerated tumor growth through the induction of IL-17A in this study." (PMID 25181290, 2014). "Depletion of IL-17A or myeloid suppressor cells resulted in tumor reduction in vivo." (PMID 24987392, 2014). "Some evidence revealed that IL-17A might promote tumor growth by stimulating angiogenesis and invasive capacity of tumor cells." (PMID 24905806, 2014). "Neutralization of IL-17A suppressed the accelerated tumor growth in pre-irradiated tumor beds." (PMID 25181290, 2014). "Other studies show that IL-17A promoted tumor growth and metastasis." (PMID 25250801, 2014). "From the standpoint of tumor immunity, it remains controversial whether IL-17A behaves as an antitumor or protumor factor." (PMID 23372655, 2013). "IL-17A has tumor-promoting effects, especially in the context of inflammation and angiogenesis." (PMID 23372655, 2013). "We determined the blockade of IL-17A at tumor sites could suppress tumor growth by inhibiting angiogenesis as well as cytotoxic T lymphocytes (CTL) activation at tumor sites." (PMID 23372655, 2013). "We speculated that the contradictory IL-17A effect on tumor growth in previous studies might be due to IL-17A function being different locally versus systemically." (PMID 23372655, 2013).
tumor (continued). "Our results were consistent with those from previous reports, and revealed that the inhibition of IL-17A expressed in tumor tissue significantly suppressed the microvessel density compared with a control model and was accompanied by lower expression of MMP9 and VEGF." (PMID 23372655, 2013). "To test this hypothesis, we inhibited IL-17A expression at tumor sites by intratumoral injection of an adenovirus vector expressing IL-17A siRNA (Ad-si-IL-17) in WT mice and examined the effects on tumor progression." (PMID 23372655, 2013). "Therefore, we planned to inhibit only local IL-17A at tumor sites by intratumoral injection of Ad-si-IL-17 and examined the role of IL-17A in tumor microenvironment on tumor growth." (PMID 23372655, 2013). "Furthermore, IL-17A produced by MDSCs recruits Treg cells at tumor sites via up-regulation of chemokines CCL17 and CCL22 and enhances their suppressor function via up-regulation of CD39 and CD73." (PMID 23372655, 2013). "We hypothesized that IL-17A that is locally produced in the tumor microenvironment has an important role in angiogenesis and tumor immunity." (PMID 23372655, 2013). "In humans, most of the studies support IL-17A contributing to tumor development." (PMID 23372655, 2013). "Since then, the influence of IL-17A on tumor development has been studied." (PMID 23372655, 2013). "In conclusion, blockade of IL-17A at tumor sites suppressed tumor growth." (PMID 23372655, 2013). "IL-17A may stimulate angiogenesis and long-term survival of tolerogenic DC, thus driving tumor growth." (PMID 23441221, 2013). "IL-17A has been described to promote Treg recruitment in tumor microenvironment." (PMID 24146810, 2013). "In addition, we investigated the mechanism of IL-17A inhibition at tumor sites with regard to tumor growth, especially in terms of local antitumor immunity involving tumor-infiltrating lymphocytes (TILs)." (PMID 23372655, 2013). "Molecular analysis revealed that IL-23 could upregulate MMP9 expression via NF-κB/p65 signaling activation and IL-17A could improve IL-23 expression in tumor cells directly via activating NF-κB/p65 signaling pathway." (PMID 23050001, 2012). "Indeed, IL-17A inhibits tumor growth in a murine model of melanoma and in implanted tumor models, while promotes malignant cell growth in mouse models of spontaneous intestinal cancer." (PMID 23109839, 2012). "It was demonstrated that IL-17A could increase the expression of IL-23 in HCC tumor cells through promoting the transcriptional expression of IL-23p40, which is the restriction expression subunit for IL-23 expression." (PMID 23050001, 2012). "Univatiate and multivariate Cox progression analysis were performed and the results showed that the frequency of IL-17A-positive cells in tumor tissue was an independent prognostic factor for overall survival (HR = 0.236, P = 0.001) and disease-free survival (HR = 0.444, P = 0.027)." (PMID 21760911, 2011). "Since overexpression of MMP is another key factor for tumor invasion and metastasis, we next investigated whether IL-17A can affect MMPs expression." (PMID 21760911, 2011). "Some reports showed that IL-17A could inhibit tumor growth and metastasis via the activation of cytotoxic T cells or inducing INF-gamma expression." (PMID 21760911, 2011). "While other studies demonstrated that IL-17A could promote cancer metastasis via affecting tumor microenvironment or inducing expression of other cytokines." (PMID 21760911, 2011). "Two out of four tumor samples showed high signal for IL-17A and one showed a weak signal." (PMID 21949768, 2011). "In addition to immune modulation, IL-17A is involved in tumor-induced bone resorption." (PMID 40536951, 2026). "Notably, IL-17A has tumor-suppressive effects under certain conditions." (PMID 40536951, 2026). "In addition to secreting IL-17A to promote tumor growth, γδ T cells also produce IL-4." (PMID 40558272, 2025).
tumor (continued). "Intraepithelial IL-17A may enhance anti-tumor responses via recruitment of cytotoxic immune cells." (PMID 41155334, 2025). "In turn, Tc17 cells may promote tumor progression by secreting IL-17A and IL-26." (PMID 40452847, 2025). "The multiple regression model investigating predictors of the IL-17A concentration, incorporating IL-8, IL-33, and tumor grade (degree of differentiation), revealed a statistically significant and robust relationship (p < 0.001), with the model explaining 70.66% of the variance in IL-17A levels." (PMID 40725273, 2025). "While this effect was not statistically significant, it supports the idea that NK cells may play a limited role in tumour control in IL17A‐proficient contexts, in line with our previous findings that CD4+ T cells are the predominant effectors in these settings." (PMID 40831074, 2025). "Additionally, IL-33 may indirectly influence IL-17A activity by modulating regulatory T cells (Tregs), thereby contributing to a suppressive tumor immune landscape." (PMID 40725273, 2025). "Interestingly, NK cell depletion in KPC/IL17A+/+ mice did not result in worsened tumour progression and appeared to be associated with more preserved tissue morphology as shown by H&E staining." (PMID 40831074, 2025). "However, other studies have shown that IL-17A may suppress tumor growth by increasing the infiltration of anti-tumor mast cells and natural killer cells while lowering the infiltration of pro-tumoral M2 macrophages." (PMID 39676857, 2024). "Further research on the effects of IL-17A on the survival and bone resorption function of mature osteoclasts may support the potential of IL-17A as a therapeutic target for the prevention and treatment of tumor BM." (PMID 38394046, 2024). "Thus, we hypothesize that M. globosa colonization in BRAC accelerates IL-17A expression and results in the chronic inflammatory response in the tumor immune microenvironment (TME)." (PMID 39235230, 2024). "In essence, the inhibition of IL-17A production in hepatic ILC3s was found to be mediated by SCFAs, synthesized in the colon and metabolized by gut bacterial enzymes, such as L. reuteri, underscoring the impact of microbiome metabolites on the tumor immune niche." (PMID 39120310, 2024). "Similarly, several studies have directly and indirectly highlighted the potential role of IL-23 in modulating tumorigenesis in humans: IL-23 plays a role in suppressing natural or cytokine-induced innate immunity and promoting tumor development and metastases independently of IL-17A." (PMID 39518685, 2024). "Evidence regarding IL-17A promotion of tumors comes from a variety of sources, whereas evidence of tumor suppression is mostly derived from immunohistochemistry, suggesting that the heterogeneity of IL-17A assay methods or tumors may have an impact on outcomes." (PMID 39676857, 2024). "Targeting IL-17A may improve tumor immune microenvironment and change ICIs response." (PMID 37978543, 2023). "How CD27− γδ T cells react to tumor-derived factors beyond IL-17A is largely unknown." (PMID 36480166, 2023). "Moreover, in the tumor tissue, a relative reduction in IL17a+ pro-tumor T cells and an increase in the IFNγ+ subpopulation was observed, possibly linked to a potential increase in responses to checkpoint inhibitor blockers, which is typically ineffective in PC." (PMID 37370753, 2023). "In addition to immune cells, some studies have suggested that tumor cells themselves might acquire the ability to produce IL-17A under certain conditions or in specific types of tumors." (PMID 37444399, 2023). "Therefore, it showed that IL-17A or IL-17F binds the receptor complex called IL-17RA–IL-17RC to drive the expression of a gene involved in the inflammation, proliferation, angiogenesis, and metastasis of primary tumor cells through NF-kB and MAPK activation." (PMID 36993955, 2023). "In addition, the other subset of γδ T cells produces IL-17A and supports tumor growth." (PMID 37511431, 2023).
tumor (continued). "Furthermore, it has yet to be shown whether IL-17A-mediated signaling during MDV results in tumor progression." (PMID 37631976, 2023). "Moreover, IL-17A expressing cells were also CD4-positive in wild-type mice, whereas in IL-17-deficient mice, we did not detect CD4/IL-17A double-positive cells, although CD4-positive cells accumulated in tumor regions as they do in wild-type mice." (PMID 38062130, 2023). "Therefore, its increase in 4T1 tumor tissue, lymph nodes, or iTh17 cells from young mice may have contributed to the enhanced iTh17 cell differentiation and IL-17A production observed in young mice." (PMID 35954312, 2022). "γδ T cells expressing gamma and delta T cell receptors (Tcrg-C1 and Trdv4) in addition to TNFa and IL-17A were a minor population of T cells yet accounted for a significant, 6-fold increase in abundance in sensitive tumors (Resistant: 0.1%; Sensitive 0.6% of total tumor residing cells)." (PMID 35924165, 2022). "In our results, it is confirmed that the expression of IL-17A, IL-17B, IL-17C, IL-17D, IL-17E (IL-25), and IL-17F in tumor immune subtypes is statistically significant, especially in BRCA; there may be a potential microenvironmental regulation mechanism that remains to be investigated." (PMID 36159856, 2022). "Moreover, we tried to determine whether the tumor immune microenvironment was different in HNSCC cancer patients with high IL17A levels compared to those with low levels." (PMID 35902909, 2022). "Thus, IL-17A and IL-6 cytokines have an inverse correlation in tumor immunology." (PMID 37529004, 2022). "Additionally, IL-17A alters the tumor microenvironment through the induction of tissue-remodeling substances, such as MMPs, inhibition of apoptosis, promotion of angiogenesis as well as recruitment of immature myeloid cells, which can suppress the activity of CD8+ T cells." (PMID 36140808, 2022). "Therefore, the A/A-genotype could increase the susceptibility to CRC, leading to an inflammatory environment through elevated levels of IL-17A in the tumor microenvironment." (PMID 36422171, 2022). "Thus, the role of IL-17A is possibly dependent on the nature of the tumor." (PMID 35883573, 2022). "Similarly, tumorigenesis of DMBA/TPA skin carcinogenesis was alleviated in IL-17A-null mice." (PMID 33922465, 2021). "ILC3s and LTi cells express the transcription factor RORγt and produce IL-17A and IL-22, cytokines that are essential to the host response to bacterial infections and maintenance of intestinal homeostasis, although their role in wound healing responses can also lead to augmented tumour progression." (PMID 33535624, 2021). "Additionally, the cytokine IL-17(A/F), which is produced by Th17 cells, may also promote tumor growth, via acting on tumor cells or other immune cells." (PMID 34943886, 2021). "Furthermore, IL‐17A expression was found on the majority of CD4+ cells in tumors analyzed, suggesting that CD4+ cells were a dominant source of IL‐17A in the tumor tissues, and implying that IL‐17A‐producing Th subsets might have a potential role on GC." (PMID 34185422, 2021). "In addition, the anti-IL17A mAb restored the ROS production of neutrophils in the tumor." (PMID 34721375, 2021). "Blocking IL-17A might enhance tumor response to anti-PD-1 therapy in MSS CRC murine models." (PMID 33462141, 2021). "However, in multiple tumor models, tumor injection induces IL-17A production by γδ T cells." (PMID 33707742, 2021). "Therefore, the depletion of IL17A may have important consequences in the tumor microenvironment targeting different cell populations." (PMID 33802061, 2021). "Interestingly, the frequency of IL-5- and IL-13-expressing ILC2s and IL-17A-producing ILC3s were positively correlated with tumour burden, suggesting that CAC development may be augmented by the local accumulation of these cytokines in the colon." (PMID 33535624, 2021). "IL-17A may also enhance tumor growth by suppressing CD4+ and CD8+ T cell infiltration." (PMID 32503584, 2020).